RNU7-10P (RNA, U7 small nuclear 10 pseudogene)
Synonyms: U7.10
Gene: Small nuclear RNA gene on chromosome 3 (17,664,963 to 17,665,025, forward strand). Ensembl gene ENSG00000271841.
Homologues: Orthologues: chimpanzee U7 (100% identical), macaque U7 (90% identical). Paralogues in human: RNU7-2P (89% identical), RNU7-7P (89% identical), RNU7-1 (87% identical), RNU7-19P (86% identical), RNU7-20P (86% identical), RNU7-8P (86% identical), RNU7-11P (84% identical), RNU7-14P (84% identical), RNU7-18P (84% identical), RNU7-25P (84% identical), RNU7-34P (84% identical), RNU7-3P (84% identical), and 142 more.